ADRB1 (adrenoceptor beta 1)
Diseases named in the same sentence as ADRB1 in open-access papers (continued):
Sharing a sentence is not in itself a finding about the gene and the disease.
cardiac hypertrophy (16 papers, 2014 to 2025). "Reports indicate THRB's regulation of genes linked to myocardial hypertrophy, including Myh6, Adrb1 and Atp2a2,28, 29 highlighting its role in myocardial remodelling and explaining the downregulation of HINT2 expression." (PMID 38546629, 2024). "Another circRNA, circSlc8a1, can affect the expression of serum response factor Srf, connective tissue growth factor Ctgf, and adrenergic receptor Adrb1 by sequestering mir-133, thereby alleviating cardiac hypertrophy." (PMID 39080192, 2024). "For example, circSlc8a1 has been found to alleviate cardiac hypertrophy by sequestering mir-133 and subsequently affecting the expression of serum response factor (Srf), connective tissue growth factor (Ctgf), and adrenergic receptor (Adrb1)." (PMID 39080192, 2024).
breast carcinoma (15 papers, 2013 to 2025). "It was shown that the product of adrenergic receptor gene ADRB1 blockers have the ability to reduce the risk of many cancer, including breast cancer." (PMID 38138918, 2023). "ADRB1 mutation was associated with lower tumor mutational burden and might serve as a potential clinical prognosis biomarker of breast cancer." (PMID 36032660, 2022). "The results indicated that high expression levels of OPN4, NOS2, GPR157, NCOA2, CLOCK, and TH were associated with shorter OS in breast cancer patients, while high expression of EGR3, NR1H3, RELB, SIAH2, and ADRB1 was linked to improved survival rates." (PMID 41031266, 2025). "Similarly, we also observed immune genes ADRB1 and chemokine ligand CCL5, which were associated with breast cancer prognosis." (PMID 38676834, 2024). "ADRB1 was considered an important target in various therapeutic applications, and studies have shown that its overexpression in breast cancer tissue may enhance tumor sensitivity to β-blockers and improve prognosis." (PMID 38676834, 2024). "ADRB1 expressed on tumor cells has been identified as a biomarker for breast cancer." (PMID 36418844, 2023). "Promising proteomic markers of breast cancer (SPG7, ADRB1, SMCO4, PHF1, and PSMG1) from NPCs identified in this study should be further verified in larger patient groups." (PMID 38138918, 2023). "In addition, the expression of ADRB1 and MRAP2 in breast cancer patients was significantly lower than in normal samples (P < 0.05)." (PMID 38676834, 2024). "Similarly to HCC, the expression of ADRB1 and ADRB2 were also significantly reduced across multiple types of human tumors such as breast cancer (BARC), cholangiocarcinoma (CHOL), colon cancer (COAD and READ), lung cancer (LUAD and LUSC)." (PMID 34593796, 2021). "Although the role of ADRB1 in breast cancer has not been fully studied, its role in other tumors suggests that it may also play an important role in breast cancer." (PMID 40826746, 2025).
cardiomyopathy (11 papers, 2012 to 2025). A disease of the heart muscle or myocardium proper. "The Beta-1 adrenergic receptor (ADRB1) gene is by far the most drug-targeted gene, with 29 different compounds from the total 56 different drugs that have been identified to interact with genes associated with cardiomyopathies." (PMID 35203258, 2022).
chronic heart failure (10 papers, 2008 to 2025). "Specifically, monoclonal antibodies to ADRB1 stimulated in vitro proliferation of T cells obtained from the blood of patients with chronic heart failure, and also increased the production of interleukin-6 by these cells." (PMID 40869214, 2025).
coronary artery disease (9 papers, 2013 to 2024). "Iron accumulation was also evident in fibrotic hearts of mice with either transgenic overexpression of the β-adrenergic receptor (Adrb1) or ischemic heart disease caused by coronary artery ligation." (PMID 38097808, 2023). "Genetically proxied ADRB1 inhibition was associated with lower risk of coronary artery disease (per 1 mm Hg lower SBP: OR 0.95, 95% CI 0.92 to 0.98; P = 1.5 × 10−3) and weakly associated with risk of stroke (OR 1.03, 95% CI 0.99 to 1.07; P = 0.18)." (PMID 35113855, 2022). "Recently, genetic polymorphisms of ADRB1 and ADRB2 have been suggested to be associated with cardiovascular events and all-cause mortality in coronary artery disease (CAD) patients, but the results of relevant studies are inconsistent and controversial." (PMID 30668166, 2019). "Among these are rs2284017 (CACNG2) for lithium (as treatment for Bipolar Disorder), rs1801252 (ADRB1) for atenolol (Coronary Artery Disease), and rs429358 (APOC1, APOE) for ritonavir (HIV, HIV infections, Hyperlipidemias)." (PMID 23758991, 2013).
atrial fibrillation (8 papers, 2010 to 2025). A disorder characterized by an electrocardiographic finding of a supraventricular arrhythmia characterized by the replacement of consistent P waves by rapid oscillations or fibrillatory waves that vary in size, shape and timing and are accompanied by an irregular ventricular response. "Flecainide was also identified previously as strongly interacting for ADRB1, with its potency effect for treating atrial fibrillation varying based on different genotypes." (PMID 40564042, 2025).
cardiac ischemia (6 papers, 2014 to 2023). "Above studies show that the increased β1-AR by cardiac ischemia is regulated by the transcription of ADRB1 gene (encoding β1-AR) possibly via cAMP/PKA/CREB pathway." (PMID 24758696, 2014).
Anxiety (5 papers, 2017 to 2025). Intense feelings of nervousness, tension, or panic often arise in response to interpersonal stresses. "Hence, these findings support our hypothesis that Adrb1-treated mice exhibit an increased exploratory drive rather than escape, anxiety- or obsessive-compulsive-related behaviors." (PMID 41365977, 2025).
depression (5 papers, 2017 to 2022). "Interestingly, among these were two genes involved in stress signalling and depressive disorders, namely Fkbp5 (encoding FK506 binding protein 5 (FKBP5), a regulator of glucocorticoid receptor (GR) activity) and Adrb1 (encoding the beta-1 adrenergic receptor (β1-AR))." (PMID 33723234, 2021). "Other targets such as ADRA1A, ADRB1, and SLC6A4 modify the occurrence of depression and other mental diseases." (PMID 35800440, 2022).
glaucoma (5 papers, 2019 to 2023). Increased pressure in the eyeball due to obstruction of the outflow of aqueous humor. "The most notable one, ADRB1, is the target of cardiovascular and glaucoma drugs, including the broad class of glaucoma drugs targeting the beta-adrenergic receptor antagonists, or beta-blockers, known to lower IOP." (PMID 37124618, 2023). "Glaucoma drugs targeting ADRB1 include topical beta-blockers, such as timolol, betaxolol, carteolol, levobunolol, levobetaxolol, and metipranolol." (PMID 36450729, 2022). "The most notable one, ADRB1, is the target of cardiovascular and glaucoma drugs, which include the broad class of glaucoma drugs targeting the beta-adrenergic receptor antagonists." (PMID 36450729, 2022).
metabolic syndrome (5 papers, 2015 to 2024). A cluster of metabolic risk factors for CARDIOVASCULAR DISEASES and TYPE 2 DIABETES MELLITUS. "With respect to Adrb1, in ob/ob mice the development of metabolic syndrome seems to be related to increased hypothalamic norepinephrine activity." (PMID 29371411, 2018).
angiosarcoma (4 papers, 2013 to 2022). A malignant tumor arising from the endothelial cells of the blood vessels. "To confirm this, we performed immunohistochemistry for the steady state protein levels of ADRB1, ADRB2, and ADRB3 on four clinically characterized human angiosarcoma tumors, revealing strong signals for ADRB1 and ADRB2 and weaker sample-dependent signals for ADRB3." (PMID 23555867, 2013). "Therefore, the purpose of the present research work was to study the mRNA expression levels of the three subtypes of the β-AR genes (ADRB1, ADRB2, ADRB3) in hemangiosarcoma (HSA) and hemangioma (HA), as well as in vascular hamartomas (VH) from dogs." (PMID 35637463, 2022).
lung carcinoma (4 papers, 2021 to 2023). "In lung cancer subtype-stratified analyses, there was weak evidence to suggest an association of genetically proxied ADRB1 inhibition with lower risk of small cell lung carcinoma (OR equivalent to 1 mm Hg lower SBP: 0.87, 95% CI 0.79 to 0.96; P = 0.008)." (PMID 35113855, 2022). "Association between genetically proxied ADRB1 inhibition and risk of overall and subtype-specific breast, colorectal, prostate, and lung cancer risk." (PMID 35113855, 2022). "The immunoreactivity of β1-adrenergic receptors (ADRB1) has been detected but not overexpressed in tumor cells, suggesting that ADRB2 plays a leading role in lung cancer compared with other beta-adrenergic receptors." (PMID 35075132, 2022).
melanoma (4 papers, 2017 to 2025). A malignant, usually aggressive tumor composed of atypical, neoplastic melanocytes. "In addition, sympathetic activity associated with stress has been shown to induce T cell exhaustion via the β1-adrenergic receptor (ADRB1), and deletion of ADRB1 enhances immunotherapy efficacy in both melanoma and pancreatic cancer." (PMID 40771813, 2025).
Stroke (4 papers, 2022 to 2026). Sudden impairment of blood flow to a part of the brain due to occlusion or rupture of an artery to the brain. "Carriers of sensitive genotypes for AGTR1, CYP2D6*10, and ADRB1 taking sensitive drugs exhibited a significantly lower risk of stroke (ORs: 0.39, 0.67, 0.68; all P < 0.01)." (PMID 41968188, 2026). "To further analyze the relationship between ADRB1 (1165G > C) polymorphism and stroke, we performed a subgroup analysis." (PMID 38298191, 2024). "Our results indicated that the CC genotype of ADRB1 (1165G > C) is a risk factor for stroke in hypertensive patients, and the risk of stroke was 1.184 times higher for the CC genotype than for the GC + GG genotype (95% CI: 1.026–1.365)." (PMID 38298191, 2024). "Univariate analysis revealed that ADRB1 polymorphism was associated with stroke (χ2 = 8.659, P < 0.05), with a higher stroke risk in the CC group than in the GC and GG groups (GC + GG)." (PMID 38298191, 2024). "Multivariate unconditional logistic regression analysis showed that the CC genotype in ADRB1 (vs. the GC + GG genotype) was associated with an increased risk of stroke [odds ratio (OR) = 1.184, P<0.05] in hypertensive patients." (PMID 38298191, 2024). "Univariate analysis revealed that the CC genotype of ADRB1 (1165G > C) was strongly associated with a higher stroke risk than the GC and CC genotypes (χ2 = 8.659, P < 0.05)." (PMID 38298191, 2024). "ADRB1 (1165G > C) gene polymorphism is associated with the risk of stroke in Chinese hypertensive patients." (PMID 38298191, 2024). "The result of subgroup analysis revealed that polymorphisms in the ADRB1 (1165G > C) gene were consistently associated with stroke in hypertensive patients regardless of BBs use." (PMID 38298191, 2024). "Therefore, ADRB1 (1165G > C) might also affect the occurrence of stroke by affecting sleep." (PMID 38298191, 2024).
acute coronary syndrome (3 papers, 2018 to 2023). Signs and symptoms related to acute ischemia of the myocardium secondary to coronary artery disease. "The influence of ADRB1 polymorphisms on blood pressure and heart rate response to beta-blocker therapy in the treatment of acute coronary syndrome (ACS) has received limited attention, particularly in the Egyptian population." (PMID 37753361, 2023).
COVID-19 (3 papers, 2021 to 2022). A disease caused by infection with severe acute respiratory syndrome coronavirus 2. "Salmeterol targets on seven non-n-COV host proteins (ADRB1, ADRB2, ADRB3, AOX1, DRD3, KCNH2, and THPO), meaning that it may not act on COVID-19 via directly targeting COV host proteins." (PMID 34539756, 2021).
lung adenocarcinoma (3 papers, 2014 to 2022). A carcinoma that arises from the lung and is characterized by the presence of malignant glandular epithelial cells. "It was worth noting that the expression of RXFP1, AVPR2, ADRB1 and VIPR1 had significantly effect on the survival of patients with lung adenocarcinoma." (PMID 36032660, 2022).
type 2 diabetes (3 papers, 2015 to 2017). "ADCY5 is also associated with type 2 diabetes and ADRB1 with adult blood pressure." (PMID 25281659, 2015).
colorectal cancer (2 papers, 2023 to 2025). A primary or metastatic malignant neoplasm that affects the colon or rectum. "A previous article reported that ADRB1 is a novel immune checkpoint in colorectal cancer." (PMID 40406147, 2025).
gestational hypertension (2 papers, 2024 to 2026). "In contrast to the previous 2-sample MR study, we found some evidence that reduced maternal SBP via ADRB1, a target of β-adrenoceptor–blocking drugs, had a potential causal relationship with lower odds of gestational hypertension, though our estimated OR was implausible." (PMID 39190310, 2024).
glioma (2 papers, 2023 to 2025). A benign or malignant brain and spinal cord tumor that arises from glial cells (astrocytes, oligodendrocytes, ependymal cells). "Glioma samples from the Cancer Genome Atlas and Human Protein Atls databases were extracted to detect the mRNA and protein expression levels of ADRB1 and ADRB2 and analyze the correlation between expression and survival of glioma patients." (PMID 41430985, 2025). "The top 5 main targets of semen strychni for the therapy of glioma were ADRB1, ADRB2, CHRM3, ADRA1A, and ESR1, based on the degree value of the software’s network function analysis." (PMID 41430985, 2025). "The core components of semen strychni used in the treatment of glioma included stigmasterol, (S)-stylopine, isobrucine, icaride A, and isostrychnine N-oxide (I), which may operate on core targets such as ADRB1, ADRB2, CHRM3, ADRA1A, and ESR1." (PMID 41430985, 2025). "Stigmasterol, (S)-stylopine, isobrucine, icaride A, and isostrychnine N-oxide (I), which may act on key targets such as ADRB1, ADRB2, CHRM3, ADRA1A, and ESR1, are the main ingredients of semen strychni used to treat gliomas." (PMID 41430985, 2025). "Data from the Cancer Genome Atlas and Human Protein Atls databases indicate that ADRB1 and ADRB2 are expressed in glioma, and high expression of ADRB2 may predict a good outcome." (PMID 41430985, 2025).
Headache (2 papers, 2022 to 2023). Cephalgia, or pain sensed in various parts of the head, not confined to the area of distribution of any nerve. "In this cohort, there were only correlations of CHRM4-Ab with immune symptoms and of ADRB1- and CHRNA1-Ab correlated with headache." (PMID 36238301, 2022).
hemangioma (2 papers, 2022 to 2025). A benign vascular lesion characterized by the formation of capillary-sized or cavernous vascular channels. "Utilizing the system’s knowledge graph, a relational chain is delineated, illustrating that propranolol, another inhibitor of ADRB1, is effectively employed in the treatment of hemangiomas." (PMID 39775838, 2025).
ovarian carcinoma (2 papers, 2019 to 2022). A malignant neoplasm originating from the surface ovarian epithelium. "From this side, the poor outcomes of BRCA1-deficient ovarian cancer patients are related to anti-apoptotic ability mediated by ADRB1." (PMID 35517499, 2022). "When inspecting the results above, we particularly noticed that genes involved in the ADRB1-mediated cAMP signaling pathway were dramatically up-regulated in BRCA1-deficient ovarian cancer patients." (PMID 35517499, 2022). "The results demonstrate that ovarian cancer cells deficient in BRCA1 express higher levels of ADRB1, which promotes the synthesis of cAMP." (PMID 35517499, 2022). "In this study, through retrospective analysis of ovarian cancer patients’ transcriptome data, we found that ovarian cancer cells in BRCA1-deficient patients expressed higher levels of ADRB1, which can enable adenylyl cyclase to generate cAMP." (PMID 35517499, 2022). "Consistent with the results above, when BRCA1 was knocked down in BRCA1 wide-type ovarian cancer cell lines, the cells expressed higher levels of ADRB1, which promoted the production of cAMP." (PMID 35517499, 2022). "We found that expression of ADRB1 in BRCA1-defective ovarian cancer cells was activated by extracellular catecholamine hormones." (PMID 35517499, 2022). "Dobutamine treatment only induced mild cAMP production, indicating that ovarian cancer cells with normal BRCA1 maintain relatively low levels of ADRB1." (PMID 35517499, 2022). "When BRCA1 was knocked down, the mRNA and protein levels of ADRB1 in the three ovarian cancer cell lines increased compared with those in the control groups, indicating that BRCA1 knock-down induces ADRB1 expression in ovarian cancer cells." (PMID 35517499, 2022). "To test this, we treated the ovarian cancer cells with the ADRB1 selective agonist dobutamine." (PMID 35517499, 2022). "In addition to ADRB1, BRCA1-deficient ovarian cancer cells also express high levels of other factors related to catecholamine-adrenoceptor-cAMP pathway regulation, such as the adenylate cyclase ADCY2 and G protein-coupled receptor ADGRB1." (PMID 35517499, 2022). "We wanted to verify whether ovarian cancer cells express higher levels of ADRB1 and upon BRCA1 knock-down." (PMID 35517499, 2022). "In addition, when we simultaneously treated the BRCA1 knock-down ovarian cancer cells with dobutamine and the ADRB1-specific antagonist atenolol, the levels of cAMP decreased to the basal level, whereas the ADRB2-specific antagonist ICI-118551 had no inhibitory effect." (PMID 35517499, 2022). "When BRCA1 was knocked down in ovarian cancer cell lines bearing wide-type BRCA1, the expression of ADRB1 was significantly increased." (PMID 35517499, 2022). "In addition, genes that involved in regulating this pathway, such as ADRB1, a β-adrenocepter that can promote the production of cAMP, were up-regulated in BRCA1-defective ovarian cancer patients." (PMID 35517499, 2022).
prostate carcinoma (2 papers, 2022 to 2025). A carcinoma that arises from epithelial cells of the prostate gland. "There was little evidence that genetically proxied ADRB1 inhibition was associated with overall risk of breast, colorectal, lung, or prostate cancer." (PMID 35113855, 2022).
alcohol dependence (1 paper, 2013). Physical and psychological dependence on alcohol. "The target of ‘Acebutolol’ is ‘Beta-1 adrenergic receptor’ (ADRB1: ADR), the disease gene of ‘Alcohol Dependence’ is ‘Gammaaminobutyric acid receptor subunit alpha-2’ (GABRA2: GABR)." (PMID 24244318, 2013).
Alzheimer disease (1 paper, 2017). A progressive, neurodegenerative disease characterized by loss of function and death of nerve cells in several areas of the brain leading to loss of cognitive function such as memory and language. "Our laboratory has also identified therapeutic potential of ADRB1 in the treatment of Alzheimer’s disease (AD)." (PMID 28746336, 2017). "The beta-1 adrenergic receptor (ADRB1) is a promising therapeutic target intrinsically involved in the cognitive deficits and pathological features associated with Alzheimer’s disease (AD)." (PMID 28746336, 2017).